EGFR (epidermal growth factor receptor)
Diseases named in the same sentence as EGFR in open-access papers (continued):
Sharing a sentence is not in itself a finding about the gene and the disease.
glioblastoma (continued). "Examples of Ovs associated with CAR-T cells are given by Ovs expressing IL-15/il-15Rα, potentiating the antitumor effect of EGFR-CAR-NK cells in GBM mouse models, or Ovs expressing IL-7, improving the efficacy of B7H3-CAR-T cells for glioblastoma therapy." (PMID 39199683, 2024). "By using the microemulsion technique and EDC/NHS, Kuo and Liang fabricated anti-EGFR mAb-grafted cationic SLN encapsulating carmustine and DOX to target and inhibit the propagation of glioblastoma (GBM)." (PMID 36678845, 2023). "As a secretory protein, C-E-Cad interacts with EGFR CR2 domain and activates STAT3, PI3K–AKT, and MAPK–ERK pathways in glioblastoma CSCs." (PMID 38933287, 2023). "Out of the three molecular alterations, EGFR amplification and +7/−10 are most specific for IDH-wildtype glioblastoma, and are strong surrogate markers for the diagnosis of glioblastoma in the absence of grade 4 histologic features." (PMID 37239289, 2023). "EGFR is also known as HER1, and its overexpression plays an important role in a variety of cancers, such as squamous-cell carcinoma of the lung, glioblastoma, and epithelial tumors of the head and neck." (PMID 36770611, 2023). "Most recently, c-Src was reported to bind and phosphorylate CD47 in an EGFR-dependent manner, which led to CD47 stabilization and immune evasion in a glioblastoma model." (PMID 37958404, 2023). "It has been demonstrated that glioblastoma cells can exist in different cellular states, and genetic alterations in different genes including CDK4, PDGFRA, EGFR, and NF1 will each favor a distinct state." (PMID 38132354, 2023). "Preclinical trials with both EGFR/EGFRvIII104 and HER2105 CAR-NK have demonstrated enhanced cytotoxicity against glioblastoma cells in vitro and resulted in increased tumor control and survival in animal models." (PMID 36792722, 2023). "EGFR (epidermal growth factor receptor)-STAT3 signaling is a fundamental pathway in tumorigenesis and propagation, and hyperactivation of EGFR is observed in 50% of glioblastoma." (PMID 38933287, 2023). "For example, in a study of glioblastoma cells, several oncogenes were found on ecDNA, including MYC, MYCN, EGFR, PDGFRA, MET, the MECOM–PIK3CA–SOX2 gene cluster, and the CDK4–MDM2 gene cluster." (PMID 37448518, 2023). "Our previous studies revealed molecules 25 and 27 as strong candidates to treat glioblastoma based on their action in two glioblastoma cell lines (U87MG and U87MG overexpressing EGFR)." (PMID 37568789, 2023). "For example, two distinct communities, Blocks 1 and 6, with the same diagnosis—glioblastoma, IDH-wildtype—yielded rather different hazard ratios: 2.76 versus 2.27, the former more likely to exhibit MGMT methylation and high EGFR amplification than the latter." (PMID 37665980, 2023). "Our results indicate that immunohistochemical detection of EGFR, MEOX2, SOX11, and INSM1 can be useful for detection of glioblastoma cells in limited histological samples, especially when used in combination." (PMID 37568909, 2023). "In glioblastoma, nuclear IGFBP2 leads to aberrant EGFR and STAT3 signaling in vitro, and RCAS-mediated IGFBP2 expression increased glioblastoma formation and progression in vivo in a mouse model, which was reversed when IGFBP2 expression was inactivated." (PMID 37029430, 2023). "Molecular profiles similarly indicated a poor-risk biological cohort including predominance of IDH-1 wild type (85.7%), MGMT unmethylated (57.1%) tumors with EGFR, PTEN, and CDKN2A profiles in keeping with molecular glioblastoma." (PMID 36402744, 2023). "EGFR amplification can affect temozolomide sensitivity in glioblastomas (GBM)." (PMID 37429858, 2023). "In glioblastoma multiforme, a sequence duplication between ZINCO1446 and EGFR on 7p11.2 creates a neo‐TAD, resulting in EGFR being aberrantly activated." (PMID 37426677, 2023).
glioblastoma (continued). "Glioblastoma’s (GBM) aggressive growth is driven by redundant activation of a myriad of signaling pathways and genomic alterations in tyrosine kinase receptors, such as epidermal growth factor receptor (EGFR), which is altered in over 50% of cases." (PMID 36831214, 2023). "To illustrate how integration of database outputs could have been used to predict differing clinical outcomes between alternative indications, we evaluate epidermal growth factor receptor (EGFR) targeting in glioblastoma (GBM)." (PMID 37457379, 2023). "It was also shown that ZR2002 is an irreversible inhibitor of EGFR, which downregulates the MAPK and PIK3 pathways leading to strong levels of apoptosis in both breast and glioblastoma cells." (PMID 36980255, 2023). "Among these alterations, the most frequent alteration is EGFR amplification, which has been observed in about 40% of all IDH-wildtype glioblastoma." (PMID 38201434, 2023). "Therefore, abnormal activation of the EGFR signaling pathway promoted the malignant progression of glioblastoma (GBM)." (PMID 37060016, 2023). "Overexpression of MUC4, a highly O-glycosylated protein, was observed in glioblastoma (GBM) cell lines and may take part in processes that promote GBM cell invasion and proliferation through upregulation of epidermal growth factor receptor (EGFR)." (PMID 37231524, 2023). "An overexpression of the epidermal growth factor receptor (EGFR) in heterozygous PTEN KO mice leads to the development of invasive glioma, which is very similar to human glioblastoma, indicating that PTEN plays a role in glioma progression." (PMID 36899941, 2023). "Overexpressed miR-429 impedes glioblastoma cell growth and migration and promotes cell apoptosis by downregulating EGFR, BCL2, and MYC, which are several oncogenes of the ERBB pathway." (PMID 37854282, 2023). "In a murine model of glioblastoma, HOXA-AS2 is a lncRNA that acts as a sponge for miR-373 through MMP-9, MMP-2, or VE-cadherin in a PIP3-kinase, serine/threonine kinase, and EGFR EGFR-dependent way." (PMID 37245177, 2023). "EGFR‐LFD showed high frequency in glioblastoma, which was 5% (7 out of 145) of total glioblastoma cases." (PMID 36622089, 2023). "The highest mutation frequency of BRAF, ATRX, IDH1, CDKN2A, and EGFR was seen in melanoma (SKCM), thyroid carcinoma (THCA), brain lower-grade glioma (LGG), head and neck squamous cell carcinoma (HNSC), and glioblastoma multiforme (GBM), respectively." (PMID 37000317, 2023). "For example, researchers used EGFR-EDV-Dox as a drug delivery system to conduct a phase I clinical trial (NCT02766699) on pancreatic ductal adeno-carcinoma and Glioblastoma Multiforme (GBM)." (PMID 37896250, 2023). "BRD4, a member of the bromodomain and extraterminal (BET) subfamily of human bromodomain proteins, whose inhibitor combined with EGFR CAR-T cells suppressed the growth and metastasis of glioblastoma cells and prolonged survival in mice." (PMID 36635683, 2023). "In glioblastoma stem cells isolated from PDX mouse models originally derived from human tumor samples, a subset of super-enhancers at the loci of critical genes, such as CDK6, SOX2, EGFR and BRD4, are shared by the majority of human glioblastoma stem cells." (PMID 38135679, 2023). "Interestingly, a recent study revealed that SEC61G can play a role in helping EGFR-amplified glioblastoma (GBM) to evade host immune elimination." (PMID 37893092, 2023). "Surface decoration specifically targeted EGFR on U87MG cell and inhibited the growth of glioblastoma." (PMID 37701520, 2023). "We therefore evaluate the clinical relevance of EGFR, MMP9, and MUC4 proteins for glioblastoma diagnosis and prognosis." (PMID 36400876, 2022). "Combination of anti-EGFR CAR T cells with JQ1 led to decreased growth and metastasis of glioblastoma cells and improved overall survival of treated mice compared to CAR T cell or JQ1 treatment alone." (PMID 35203517, 2022).
glioblastoma (continued). "TLK2 is reported to complex with Src and activate EGFR/Src/FAK signalling pathway to promote the migration and invasion in breast adenocarcinoma and glioblastoma cells." (PMID 35064619, 2022). "To determine the mechanism responsible for this reduced HGF/MET signaling in oval cells with C3G down-regulation, we search for a potential alteration in MET membrane localization and/or recycling as C3G facilitates recycling and membrane localization of EGFR in glioblastoma (GBM) cells." (PMID 36263169, 2022). "Four of these seven cases relate to glioblastoma in which fusion pairs CAPZA2-MET and FIP1L1-PDGFRA, CAPZA2-MET and MET-MET, EGFR VIII and PTPRZ1-MET, PTPRZ1-MET and TBL1XR1-PIK3CA were identified." (PMID 35984852, 2022). "In addition, it has been well documented that aberrantly high activation of EGFR signal pathway drives progression of glioblastoma, and EGFR is identified as a direct target of miR-137 in GBM." (PMID 35965517, 2022). "In SK-MG1 glioblastoma cells, while CD109 attenuates TGF-β signaling, it also enhances epidermal growth factor receptor (EGFR) signaling." (PMID 35954339, 2022). "To represent this molecular characteristic we used glioblastoma cell lines, U87MG, and the same ones engineered to overexpress wild-type (wt) EGFR or EGFRvIII to explore the iPA antiproliferative effect." (PMID 35393392, 2022). "In addition to the link identified between CD73 and EGFR-amplified AC-like adult glioblastoma, scRNA-seq showed that CD73 expression may be independently associated with OPC-like high-grade gliomas in pediatric patients, some of whose tumors also exhibit elevated PDGFRA expression." (PMID 35973991, 2022). "The results disclosed 27 molecules (18 EGFR, 6 PI3Kp110β, and 3 dual inhibitors) for biological validation, performed in two glioblastoma cell lines (U87MG and U87MG overexpressing EGFR)." (PMID 35884571, 2022). "Here, we developed GNPs that cross the BBB and shuttle anti-epidermal growth factor receptor (EGFR) antibodies into the brain, to actively target the commonly amplified EGFR in glioblastoma." (PMID 36324626, 2022). "The presence of an extra copy of chromosome 7 has been correlated with the aggressiveness of glioblastomas with increased expression of the mitogens BRAF, EGFR, HOX5A, MET, and PDGFA." (PMID 36077131, 2022). "A study reported that the molecular classification of glioblastoma involving IDH1, PDGFRA, EGFR, and NF1 substantially benefits the prediction of prognosis and response to therapy in glioblastoma patients." (PMID 36090889, 2022). "In particular, the 790 human glioblastomas analyzed by Bredel and coworkers revealed either an EGFR amplification or an NFKBIA deletion, with heterozygous deletions of NFKBIA being present in 28% of glioblastomas and in 22% of cancer stem-like cells." (PMID 35203471, 2022). "PRMT1 and PRMT5 regulate the EGFR signaling pathway by methylating EGFR (in colorectal and TNBC cells), or by methylating histones on the EGFR promoter (in glioblastoma or colorectal cells) to regulate its transcription." (PMID 35053470, 2022). "CX-4945, when administered with gefitinib, an epidermal growth factor receptor (EGFR) inhibitor, exerted a strong antiproliferative effect on glioblastoma in vitro." (PMID 35214064, 2022). "Intracranial injections of bispecific EGFR- and EGFRvIII- targeted CAR-NK-92 prolonged the survival of glioblastoma xenograft mouse." (PMID 36324149, 2022). "Researchers discovered that EGFR, c-MYC, N-MYC, and other genes depend on a large number of ecDNA amplification copies in glioblastoma cells." (PMID 35614494, 2022).
glioblastoma (continued). "In the context of glioblastoma, invasion, scatter factor/hepatocyte growth factor (SF/HGF), and epidermal growth factor receptor (EGFR) act on cell motility." (PMID 35053605, 2022). "As An et.al demonstrated that EGFR cooperated with EGFRvIII to induce CCL2-mediated TAMs recruitment in GBM, we investigated CCL2 expression in glioblastoma cells under TMZ treatment." (PMID 36230833, 2022). "Enhancement or alterations of PDGFRA, EGFR, insulin-like growth factor receptor (IGFR-1), and basic fibroblast growth factor receptor 1 (FGFR1) accounts for 80% of the primary glioblastoma." (PMID 36185622, 2022). "This study also postulates how aging contributes to the onset and origin of glioblastoma by increasing the gene expression of NF-κB, REST/NRSF, ERK, AKT, EGFR, and others." (PMID 35538578, 2022). "Oncogenes including EGFR, PDGFRA, ERBB2, and Proto-Oncogene tyrosine-protein kinase (KIT) are found on ecDNA in glioblastoma and are amplified in huge numbers that have a key role in cancer promotion, according to research." (PMID 35614494, 2022). "EGFR and HER2, which are highly expressed in human glioblastoma and other tumor cells, have been widely applied for OV engineering." (PMID 36159398, 2022). "In glioblastoma cells, NK1R-mediated EGFR transactivation was involved with a PTX-sensitive Gα protein; activated EGFR complex was found to contain adaptor proteins SHC and Grb2." (PMID 35013118, 2022). "Additionally, driving EGFR could induce ferroptosis in hepatocellular carcinoma and glioblastoma." (PMID 35359830, 2022). "Amplification of Platelet-Derived Growth Factor Receptor Alpha (PDGFRA), EGFR, and MET genes is also observed in IDH-wild-type glioblastomas." (PMID 35989351, 2022). "PRMT1 has been previously observed to modulate EGFR signaling by two mechanisms: (i) by methylating histone H4 (H4R3me2a) on its promoter in colorectal cancer (CRC) and glioblastoma cells and (ii) by methylating EGFR in CRC and TNBC cells." (PMID 35053470, 2022). "Further, the Epidermal Growth Factor Receptor (EGFR), a critical factor in tumor malignancy in several cancer types, including glioblastoma, has emerged as one of the most explored drug targets in cancer therapeutics over the past 20 years." (PMID 35912242, 2022). "For instance, EGFR mediated the efficacy of CAP in killing EGFR-overexpressing oral squamous cell carcinoma cells and the expression of death receptors such as TNFR1 and DR4/5 were noticeably enhanced in glioblastoma cells after CAP treatment." (PMID 36551308, 2022). "This study also postulates how aging contributes to the onset of glioblastoma by dysregulating the gene expression of NF-κB, REST/NRSF, ERK, AKT, EGFR, and others." (PMID 35538578, 2022). "As can be seen, this analysis revealed downregulation of ErbB (EGFR) and mammalian target of rapamycin (mTOR) signaling in addition to several other pathways that promote the growth and survival of glioblastoma in both cell lines following GZ17-6.02 treatment." (PMID 35456993, 2022). "Han reported that EGFR-CAR-engineered NK cells displayed enhanced cytolytic capability and production of IFN-γ, which restrained glioblastoma growth and obviously prolonged the survival of tumor-bearing mice." (PMID 36324149, 2022). "In glioblastoma, YY1 acts as an oncogene that stimulates EGFR expression via miRNA effects, in turn, promoting cellular proliferation." (PMID 35999564, 2022). "In glioblastoma cell lines, PHD3 increases the levels of phosphorylated epidermal growth factor receptor (EGFR) by inhibiting receptor internalization." (PMID 33799686, 2021). "The combined NF1, RAF, and RTK alterations from EGFR, PDGFRA, FGFR3, and Multi-RTK subgroups that activate the ERK/MAPK signaling pathway accounted for 85% of the glioblastoma IDH-wild-type cases." (PMID 34572759, 2021). "We also observed an exclusion between IDH1 and EGFR, IDH1 and PTEN, along with a co-occurrence between EGFR and PTEN, which often appeared in glioblastoma." (PMID 34307451, 2021).
glioblastoma (continued). "It has been reported that human cord blood MSCs decrease the cellular invasion and migration of a glioblastoma cell line through their downregulation of PI3K/AKT, c-Myc/ERK, and EGFR/c-Met activities." (PMID 34944000, 2021). "We found that Lpd and EGFR mutually co-operate and Lpd interacts with the rapamycin-insensitive companion of mTOR (RICTOR) consequently critically co-regulating glioblastoma invasion and radiation sensitivity." (PMID 34771501, 2021). "In a pre-clinical model of glioblastoma multiform (GBM), ACD results in the generation of daughter cells with EGFR-mediated enhanced therapeutic resistance." (PMID 34587981, 2021). "The integrated genomic and transcriptomic analysis of the tumors showed EGFR, PDGFRA, FGFR3, NF1, and BRAF/RAF1 mutually exclusive alterations within the glioblastoma IDH-wild-type category." (PMID 34572759, 2021). "Differential expression brain-derived proteins, such as the EGFR, MMP9, TIMP, and fibulin-2 and−5, were validated to be released at the same time in one study of high-grade glioblastomas." (PMID 33708196, 2021). "By immunizing mice with purified recombinant hEGFR ectodomain (hEGFRec) from cultures of hEGFRec-overexpressed human glioblastoma, LN229, cells, we previously developed a novel anti-human EGFR (hEGFR) monoclonal antibody (mAb), namely EMab-134." (PMID 34944112, 2021). "Of all misclassified histological WHO grade 4 IDH-wildtype glioblastoma patients in our four validation sets, only 19% showed IDH-wildtype glioblastoma-like SCNA features + 7/ − 10 or EGFR amplification." (PMID 34863298, 2021). "The NF1 and RAF subgroups accounted for almost one-quarter of the glioblastoma IDH-wild-type cases, with the NF1 subgroup being the second largest after the EGFR subgroup." (PMID 34572759, 2021). "The glioblastoma resistance to various therapies is mainly due to an extremely mutated genome and over-activation of tyrosine kinase receptors, such as EGFR, PDGFR and VEGFR, which are usually up-regulated in glioblastoma." (PMID 33525678, 2021). "In the pancreatic cancer cell line BxPC-3, CHIP ubiquitinates and promotes the degradation of epidermal growth factor receptor (EGFR), and overexpression of CHIP suppresses cell growth and is consistent with a tumor-suppressive role for CHIP in glioblastoma." (PMID 34831344, 2021). "In adequacy with our findings, other studies showed similar results by suggesting an anti-proliferative role of miR-7-5p through targeting the EGFR, MAPK and IGF1R/Akt signaling pathways in different tumoral contexts, such as glioblastoma and tongue carcinoma." (PMID 34381564, 2021). "EGFR overexpression in glioblastoma (GBM) drives cell invasion and tumour progression." (PMID 34831480, 2021). "In conclusion, our current findings have identified that the EGFR and EGFRvIII drive RCN1 gene and protein expression which protects glioblastoma cells from apoptosis when challenged with inducers of ER stress." (PMID 33801941, 2021). "To demonstrate effects of antitussive compounds on the growth of glioblastoma cell lines, we used U87MG, temozolomide-resistant U87MG-TMZR, lapatinib (EGFR inhibitor)-resistant U87MG-LAPAR, and chemoresistant T98G." (PMID 33980886, 2021). "Mutations of anabolic signaling proteins phosphoinositide 3-kinase (PI3K), epidermal growth factor receptor (EGFR), and isocitrate dehydrogenase types 1 and 2 (IDH1, IDH2) have been widely detected in glioblastoma patient biopsy samples." (PMID 34769339, 2021). "Epidermal growth factor receptor (EGFR) has been regarded as a potent oncogene and clinical marker in glioblastoma." (PMID 34575486, 2021). "EGFR is frequently constitutively active in glioblastoma (GBM)." (PMID 33420027, 2021). "RRAD expression is reported to promote cell survival via activation of the EGFR/STAT3 signaling pathway and stimulate glioblastoma cell migration." (PMID 33980886, 2021).